CD86 (CD86 molecule)
Diseases named in the same sentence as CD86 in open-access papers (continued):
Sharing a sentence is not in itself a finding about the gene and the disease.
tumor (continued). "In myeloid cells, this is observed by a significant increase in CD86+ classical monocytes and CD123+ nonclassical monocytes in patients with PDAC and benign disease." (PMID 38686549, 2024). "Similarly, the loss of COX2 did not alter the frequency of tumor-associated macrophages (TAM) but induced proinflammatory polarization of both CD11b+ and CD11c+ TAMs with increased expression of both CD86 and MHC II as well as decreased expression of the M2 markers arginase and CD206." (PMID 38635884, 2024). "CD31 acts as a co-inhibitory receptor, where CD31+ DCs are more tolerogenic, suggesting in the absence of FGL2 cDC2s in B16F10 tumours are more activated (MHCII+, CD86+, CD40+) and less immunosuppressive (CD31+)." (PMID 38191799, 2024). "CD86, but not CD80, blockade prevented the effector Treg response, enriched the tumor-draining lymph node migratory conventional DCs that were positive for PD-L1 and CD80 (PD-L1+CD80+), and promoted CTL priming." (PMID 38349740, 2024). "Next, we investigated the effect of CAR/CCR-redirected T cells on non-tumor B cells, which usually express CD19 but no CD80 or CD86 on their surface when not activated." (PMID 38340727, 2024). "Our results showed that LPS-treated BMDCs did not exhibit any changes in MHC-2 and CD86 surface expression, while BMDC stimulation with B16F10 and MOC2 tumor cell lysates resulted in differential MHC-2 expression in response to ISO treatment." (PMID 37006295, 2023). "The percentage of CD86+ and CD206+ macrophages was significantly higher in the non-irradiated tumors compared to the irradiated tumor of the Abseff group." (PMID 36944686, 2023). "The DCs present in the tumor were positive for H-2Kb, but not for CD40 or CD86, while the DCs in lymph nodes were positive for CD40." (PMID 36551577, 2022). "CD86+ macrophages were significantly increased in tumor after 72 h treatment with HB3089, while no significant increase observed in blood and tumor of 24 h treatment." (PMID 36513640, 2022). "Even in the absence of tumour cell apoptosis, cGAMP treatment-induced DC maturation, manifested by 4-, 6-, and 2-fold increases of CD80, CD86, and MHC-II, respectively, compared to PBS treatment." (PMID 34285232, 2021). "Immunohistochemistry (IHC) staining validated that CD86 expression was correlated with MGMT status and X1p/19q subtypes, which is independent of tumor grade." (PMID 33954112, 2021). "Although tumor cells possess MHCI molecules, there are no co-stimulation signals (CD80 and CD86), which are necessary for the final maturation of cytotoxic T cells." (PMID 33824314, 2021). "In vivo data overall agreed with the in vitro results, showing increased expression of CD80, CD86, MHC-II, and GBP5 indicative of M1-like activation in tumor grafts not depleted of macrophages." (PMID 34488792, 2021). "The inflammation markers showed extremely scarce staining: CD86 did not present significant staining, and neither did CD68 but depicted unusual marking mostly at the superficial periphery of the tumor." (PMID 34830041, 2021). "IHC staining validated that CD86 expression was correlated with MGMT status and X1p/19q subtypes, which was independent of tumor grade." (PMID 33954112, 2021). "In absence of TLR stimulation, circulating and tumor‐infiltrating 20 h‐cultured cDC2s and pDCs displayed higher levels of CD80, CD40 and/or CD86 (% and/or MFI) when compared to HD." (PMID 33282290, 2020). "By contrast, STAT3 did not affect expression of CD86, CD80, or MHC II on vaccine-derived CD103+ cDC1s within tumor-draining lymph nodes (TdLNs)." (PMID 31947933, 2020). "The experimental data showed that the protein expression of CD40, CD80, CD86, and HLA-DR on CD1c+ DCs was downregulated after co-culture with primary NSCLC cells compared with that on CD1c+ DCs that were not cocultured with tumor cells." (PMID 31921114, 2019). "We found that MC38 and LLC tumor cells do not express CD80 and CD86 costimulatory molecules and this phenotype is not modified by CIITA expression." (PMID 31417570, 2019).
tumor (continued). "In this setting, mPGES-1−/− monocyte-derived tumor spheroid-infiltrating macrophages indeed expressed higher CD80, but not CD86, levels compared to wildtype macrophages." (PMID 25871398, 2015). "Both immunostimulatory CD8α + and CD8α- DC subsets were increased, whereas expression of activation markers CD40, CD70, CD86, and of MHC Class I molecules in either subsets of tumor infiltrating DCs were not altered by CD1d blockade." (PMID 25349699, 2014). "DCs from the non-adherent cell fraction in the DC/tumor electro-fusion products had significant up-regulation of MHC class II as well as CD80, CD86 and CD83." (PMID 24466232, 2014). "The ethanol-treated and untreated tumor cells (PANC/Mock and PANC/TGF-β) showed sustained expression of HLA-ABC, HLA-A2, MUC1, TLR2, and TLR4, but not HLA-DR, CD80, CD86, and CD83 (data not shown)." (PMID 23717436, 2013). "In contrast the co-stimulatory receptors (CD80, CD86) and CD83 are not influenced by the tumor, HLA-DR expression is even decreased in many cases and the early activation marker CD25 is only presented by a small subpopulation [unpublished data]." (PMID 21264308, 2011). "Intraperitoneal injection of the anti-CD25 monoclonal antibody PC61 reduced Treg frequency in blood and tumors, but did not affect the frequency of tumor-infiltrating dendritic cells, or their expression of CD40, CD86 and MHCII." (PMID 21390236, 2011). "Mouse bone-marrow-derived DCs first activated with the TLR4 ligand LPS and exposed to tumor-induced Treg maintain expression of CD80, CD86, and CD40, produce IL-12 or TNF-a, and are not impaired in their allostimulatory activity." (PMID 22110524, 2011). "Furthermore, there was no significant change in tumor cell phagocytosis or the expression of co-stimulatory markers CD80 and CD86 when compared to NDV alone." (PMID 41322194, 2025). "Similarly, mainly NPC cell, but not CD68+ CD86+ M1 and CD68+ CD206+ M2 macrophage-derived PD-L1 protein was increased in tumor samples from responders." (PMID 38448521, 2024). "PD-L1 expression in tumor cells and lymphocytes was associated with a poor prognosis in a study evaluating the expression of CD80, CD86, and PD-L1 in both the tumor and lymphocytes in renal cell tumor cases in the literature, whereas CD80 and CD86 expressions were not correlated with the prognosis." (PMID 37614091, 2024). "The expression of MHC class I (p < 0.05, partial η2 = 0.58), MHC class II (p < 0.01, partial η2 = 0.87), CD80 (p < 0.01, partial η2 = 0.83), and CD86 (p < 0.01, partial η2 = 0.69) significantly increased with the pulsation of EL4 tumor lysate with VP-R8 compared to non-pulse treatment in vitro." (PMID 38892182, 2024). "Interestingly, in our study, the proportion of CD11b−F4/80+ cells in the spleen showed a positive correlation with tumor weight, whereas the proportion of CD86+ cells and CD80+ cells in CD11b−F4/80+ cells showed a negative correlation with tumor weight." (PMID 37553633, 2023). "At early stages of tumor response (i.e., when tumor’s progression stopped), we indeed showed that Lipo-MP-LPS induces an early tumor infiltration by CD3+CD4+CD25+ T helper cells, but not Treg, and increases the levels of CD68+CD86+ M1 macrophages in tumors." (PMID 37760603, 2023). "Whereas DC numbers and CD86 expression were comparable in tumors from these animals, the frequencies of active IFN-γ-expressing CD8+ T cells in the tumor (but not splenic) tissues were increased by ablation of ATF3 but decreased in response to the loss of CH25H in DCs regardless of the ATF3 status." (PMID 36333297, 2022). "They expanded memory Vδ1 subpopulation using engineered APCs expressing CD86, 4-1BBL, CD40L and the CMV-antigen-pp65, obtaining polyclonal γδ T cells expressing activation and memory markers, with potent anti-tumor activity in vitro and in vivo with no sign of alloreactivity." (PMID 33450862, 2021).
tumor (continued). "Studies 24 have shown that in the tumor microenvironment, anti-CTLA-4 stimulates the activation of surrounding T cells by blocking the binding of CTLA-4 on the surface of T cells to the ligand CD80/CD86 on APCs, but does not activate T cells." (PMID 33531977, 2021). "CTLA4-T cells efficiently lysed CD80-positive or CD86-positive tumor cells (Raji, RL, and NALM6), but not CD80/CD86-negative K562 cells, whereas control effector cells (GFP-T) could not initiate specific lysis on either cell line." (PMID 33868277, 2021). "Studies 36 have shown that in the tumor microenvironment, anti-CTLA-4 stimulates the activation of surrounding T cells by blocking the binding of CTLA-4 on the surface of T cells to the ligand CD80/CD86 on APCs, but does not activate T cells." (PMID 33391454, 2021). "One study found that inducible IL-12 allowed CAR T cells to eradicate antigen-positive tumor cells and prevent outgrowth of antigen negative tumor cells by recruiting and activating macrophages to produce TNFα and upregulate costimulatory molecules CD80/CD86 to enhance T cell responses." (PMID 34177932, 2021). "Also, most primary tumor cells lack expression of costimulatory molecules such as CD80, CD86, and ICOSL, and T cell anti-tumor responses can be compromised by lack of costimulation." (PMID 32038630, 2019). "In addition, most tumor cells, especially non-hematopoietic tumor cells do not express ligands of CD28, CD80, and CD86." (PMID 31001256, 2019). "Tumor cell killing by IFN-γ/LPS-activated peritoneal macrophages was completely abrogated in the absence of iNOS (p < 0.001), despite preserved macrophage activation as indicated by increased surface expression of MHC class II and CD86 (data not shown)." (PMID 30083157, 2018). "The 4T1 tumor cells did not further increase the maturation marker expression of mDCs, whereas the antigen-presenting molecules MHC-I and MHC-II and the co-stimulatory molecules CD80 and CD86 were markedly reduced on DCs stimulated by irradiated 4T1 cells." (PMID 27551446, 2015). "This suggested that CD86, but not CD80, might be involved in the CTLA4Ig-mediated anti-tumor activity by regulating NK cell function." (PMID 24349559, 2013). "Since tumor-bearing mice depleted for CD8+ T cells and Tregs showed complete tumor rejection, we analyzed in this group for CD11b+F4/80+ macrophage activation (expression of CD86) at day 6 ptc in lymph nodes in comparison with non-depleted and naïve animal." (PMID 22890822, 2013). "We aimed to enhance the effect of tumor lysate with regard to induction of DC maturation, but as reported by others we had to face the problem that the tumor lysate rather did not induce DC maturation, in terms of upregulation of surface markers CD40, CD80, and CD86." (PMID 21615909, 2011). "Immunofluorescent analysis of primary tumor tissues further revealed a dose-dependent increase in phosphorylated STAT1 within M2 TAMs (pSTAT1+/CD206+) following rWISP-1 treatment in a dose-dependent manner, whereas no significant change was observed in M1 TAMs (pSTAT1+/CD86+)." (PMID 41522359, 2026). "Moreover, the total macrophages (Mφ; F4/80+), M1 phenotypical Mφ (F4/80+CD86+) and M2 phenotypical Mφ (F4/80+CD206+) were all greatly increased in tumour tissues regardless of the treatment received when compared with PBS, but the OMVs plus NIR treatment triggered the greatest changes." (PMID 40240911, 2025). "When compared to exosomes from tumor cells without heat stress (TEX), heat-stressed tumor cell-derived exosomes (HS-TEX) had more chemokines (CCL2, CCL3, CCL4, CCL5, and CCL20), HSPs (HSP60, HSC70, HSP70, and HSP90), and adhesion molecules (e.g., CD54 and CD86)." (PMID 35158999, 2022). "CD86-positive moDC fraction was decreased in cultures with exosomes derived from MKN74 + EBV and SNU719 compared to that with exosomes derived from MKN74, indicating that EBV-infection imposes a negative effect on the induction of tumor immunity via their exosomes." (PMID 33198173, 2020).
tumor (continued). "Moreover, regardless of costimulation from the tumor cell, anti-CD19 AbTCR-T cells had similar anti-tumor activity compared to CAR-T cells in both Raji and CD80-/CD86- tumor models." (PMID 30479831, 2018).
infection (415 papers, 2004 to 2026). The state of being infected such as from the introduction of a foreign agent such as serum, vaccine, antigenic substance or organism. "When we segregated the subpopulations of neutrophils by markers, Kp52145 was only found within CD86- neutrophils and predominantly associated with PD-L1+ cells at any time point post infection." (PMID 38578798, 2024). "Only high-MOI (50 pfu/cell) rCPIV-infected DCs underwent DC maturation (CD80, CD86 expression), and infection at a low MOI (10 pfu/cell) caused only high expression of CD86 and partial maturation of DCs." (PMID 38173672, 2023). "Dendritic cells from IL-22-deficient mice express significantly more CD86 compared to dendritic cells from wt mice at this early time point of infection." (PMID 27311945, 2016). "At 40 hours post infection, we examined the expression levels of markers associated with DC maturation including CD86, CD80 and CD54." (PMID 27930745, 2016). "Additionally, L. monocytogenes-induced necrosis resulted in a loss of CD86 expression on dendritic cells 48 h post infection relative to wild type immunizations." (PMID 29324702, 2018). "Moreover, in vitro and in vivo studies have shown that increased expression of CD80 and concomitant decreased expression of CD86 are associated with a more severe infection and inflammation, whereas increased expression of CD86 in septic patients is thought to have a protective function." (PMID 37213504, 2023). "In comparison, when MAR-5A3 was administered on day 4 after WNV-NY infection and splenocytes analyzed on day 6, we observed a reduced percentage of CD11b+ (P<0.01) and CD11c+ (P<0.02) cells, and this was associated with decreased expression of CD86 only on CD11c+ cells (P<0.008)." (PMID 22144897, 2011). "RT-qPCR analysis demonstrated significant upregulation of M2 markers (Cd206 and Mr) following infection, with minimal changes in M1 markers (Cd86 and Nos2)." (PMID 40248690, 2025). "MHC class I (MHC‐I, HLA‐A/B/C) expression remained largely unaltered, while CD80 or CD86 costimulatory molecules were undetectable at baseline or upon infection." (PMID 39535369, 2025). "There was a significant influx of CD11c+ dendritic cells in MLN of the IL-33–treated group prior to the infection; however, only a small number of these dendritic cells expressed activation markers such as CD86." (PMID 40048372, 2025). "We also demonstrated the RSV infection-induced activation of monocytes via the expression of CD80, CD86, and HLA-DR on the cell surface upon infection." (PMID 41280933, 2025). "Higher expression levels of CD86 were also found on macrophages in the lungs of KP1088PC-infected mice when compared with mutant-mediated infection and the Sham group." (PMID 39950808, 2025). "In the case of co-stimulatory molecules, Cd40 and Cd86 were both upregulated by infection, with IFNγ further amplifying this effect." (PMID 40547518, 2025). "The results demonstrated low Il1b, Ifng, and Cd86 mRNA expression during ME49 ∆bfd2 strain infection." (PMID 40906736, 2025). "At day 2 after infection, significantly more CD11c+ dendritic cells with higher expressing activation marker CD86 were found in MLN, but this difference was no longer observed by day 5 of infection." (PMID 40048372, 2025). "Next, we investigated the activation status of dendritic cells (CD11c+CD86+) three days after tuft cell activation with denatonium or three days after infection with P. aeruginosa in tracheae and lungs." (PMID 39794305, 2025). "Similar to Type II infection, dendritic cells responding to avirulent Δplp1 parasites were phenotypically more activated at 3 dpi than those in RH infected mice, as measured by CD86 expression." (PMID 40166190, 2025). "It was shown that under hypoxia, there is a reduction in CD80 and CD86 expression and an increase in the production of IL-12p70, which has an impact in the control of the infection of DC with L. amazonensis." (PMID 38787051, 2024).